BCL2L1 (BCL2 like 1)
Diseases named in the same sentence as BCL2L1 in open-access papers (continued):
Sharing a sentence is not in itself a finding about the gene and the disease.
glioma (100 papers, 1999 to 2025). A benign or malignant brain and spinal cord tumor that arises from glial cells (astrocytes, oligodendrocytes, ependymal cells). "In addition, the study identified CLU and BCL2L1 as key players in glioma progression, but the detailed molecular mechanisms underlying their interactions remain to be fully elucidated." (PMID 40606578, 2025). "Collectively, these results suggest that CLU accelerates cell migration and growth while inhibiting apoptosis in glioma cell lines primarily through the upregulation of BCL2L1." (PMID 40606578, 2025). "Collectively, these in vivo results demonstrate that CLU promotes glioma formation, with its effects mediated through the upregulation of BCL2L1." (PMID 40606578, 2025). "In summary, our study provides compelling evidence that CLU plays a significant role in glioma progression by enhancing cell migration and proliferation, while inhibiting apoptosis primarily through the upregulation of BCL2L1." (PMID 40606578, 2025). "Collectively, these results demonstrate that CLU promotes glioma formation in vivo, with its effects mediated through the upregulation of BCL2L1." (PMID 40606578, 2025). "The current study’s findings are based on experiments conducted in nude mice, which provided valuable insights into the role of CLU and BCL2L1 in glioma progression." (PMID 40606578, 2025). "Consistent with prior evidence, KO of BCL2L1 led to a concentration-dependent sensitization of both adult and pediatric gliomas toward MCL1 inhibitors." (PMID 39846250, 2025). "Immune-related genes GZMB, HLA-A and BCL2L1 were significantly over-expressed in high-grade glioma patients (p < 0.001, versus low-grade glioma patients) and a concordance between differentially expressed genes in plasma- and glioma-derived RNA was reported." (PMID 37091783, 2023). "The findings above established a connection between CLU and BCL2L1, but whether CLU promotes glioma via BCL2L1 remained unclear." (PMID 40606578, 2025). "Functional assays revealed that CLU and BCL2L1 promoted glioma cell migration and proliferation." (PMID 40606578, 2025). "The complex interplay between CLU, BCL2L1, and other signaling pathways may vary across different glioma subtypes and genetic backgrounds." (PMID 40606578, 2025). "Furthermore, the magnitude of fold change of the BCL2L1 gene was observed to be higher in patients with high-grade glioma compared to patients with low-grade glioma." (PMID 34643804, 2022). "Moreover, some evidence suggests that high levels of BCL2L1 protein expression prevent the death of cancer cells such as glioma." (PMID 36354566, 2022). "Moreover, the fold change of the BCL2L1 gene was observed to be higher in patients with high-grade glioma (p = 0.022, versus low-grade glioma patients)." (PMID 34643804, 2022). "Moreover, STAT5B can drive tumour progression in a PDGFB-driven glioma model and this involves increased BCL2L1 expression." (PMID 33478100, 2021). "Moreover, it was confirmed that a knockdown of PDAM in glioma cells induced cisplatin resistance mainly because of the up-regulation of the anti-apoptotic gene, BCL2-like 1 (BCL2L1)." (PMID 31652459, 2019). "Substrates affected include FOXO transcription factors (FOXO3 and FOXO4) and BCL-2 protein family (BAD, BCL2, and BCL2L1) in which the phosphorylated state may ensure glioma cell survival under stressful environments." (PMID 21955618, 2011). "Furthermore, both in vitro and in vivo experiments confirm that CLU’s pro-tumorigenic effects are mediated by BCL2L1, suggesting that targeting this pathway could be a promising therapeutic strategy for glioma treatment." (PMID 40606578, 2025). "The BCL2L1 gene was observed to be significantly over-expressed in the plasma samples of glioma patients relative to healthy controls, and its fold change was observed to be relatively higher in the plasma samples of patients with high-grade glioma compared to patients with low-grade glioma." (PMID 34643804, 2022).
glioma (continued). "Bioinformatics analysis using TIMER2.0 and GEPIA 2.0 revealed positive correlations between CLU expression and several genes (BAX, BCL2L1, PRNP, HSPA5, LRP2, TTR, all p < 0.05), suggesting synergistic or antagonistic interactions during glioma development." (PMID 40606578, 2025). "We identify BCL2L1 DNA methylation as a key biomarker predicting MCL1 dependency, offering targeted MCL1 inhibitor therapy for pediatric high-grade gliomas and other cancers." (PMID 39846250, 2025). "Inhibiting BCL2L1 reversed the pro-migratory and pro-proliferative effects of CLU overexpression and restored apoptosis in glioma cells." (PMID 40606578, 2025). "Analysis of glioma patient data revealed a positive correlation between CLU and BCL2L1 expression." (PMID 40606578, 2025).
glioblastoma (95 papers, 2008 to 2025). The most malignant astrocytic tumor (WHO grade IV). "Overexpression of miR-342 resulted in enhanced apoptosis and decreased Bcl2-L1 proteins in glioblastoma cells." (PMID 37736508, 2023). "Glioblastoma cell lines such as U251 and u87 when treated with miR-342 resulted in the reduction in the expression of anti-apoptotic genes Bcl2-L1 and Mcl-1." (PMID 37736508, 2023). "In fact, STAT5B can be activated by SFKs and mediate survival signalling in glioblastoma cells through direct activation of the BCL2L1 promoter." (PMID 33478100, 2021). "Notably, the critical anti-apoptotic protein, BCL-xL/BCL2L1, is highly expressed in GSCs and glioblastoma stem-like cells (GSLCs) cultured using the tumorsphere method in comparison to differentiated cells and prevents intrinsic apoptosis induced by alkylating agents." (PMID 35740330, 2022).
hepatocellular carcinoma (87 papers, 2006 to 2025). A malignant tumor that arises from hepatocytes. "In hepatocellular carcinoma, the presence of let‐7a‐5p is speculated to result in BCL2L1 suppression, ultimately resulting in apoptosis of cancerous hepatocytes." (PMID 36545841, 2023). "Several solid tumors, like sarcomas, prostate, breast, pancreatic, lung, colorectal, and liver carcinomas, show ATP1A1/BCL2L1 levels below the average in the TCGA pan-cancer analysis." (PMID 37904054, 2024). "In addition, KEGG analysis indicated the involvement of apoptotic pathways, including “platinum drug resistance,” “hepatocellular carcinoma,” “thyroid hormone signaling pathway,” and “amyotrophic lateral sclerosis”, as highlighted by the decreased expression of A0A0S2Z3C5 (BCL2L1) and P60709 (ACTB)." (PMID 39562369, 2025).
lymphoma (87 papers, 2006 to 2026). A malignant (clonal) proliferation of B- lymphocytes or T- lymphocytes which involves the lymph nodes, bone marrow and/or extranodal sites. "BCL-XL (encoded by the Bcl2l1 gene) was consistently overexpressed by lymphoma cells at both the RNA level and protein level in our mouse model." (PMID 34140493, 2021). "To confirm the importance of Bcl-xL in ALCL, we made use of the Piccaluga Lymphoma dataset and observed significant upregulation of BCL2L1 (Bcl-xL) expression when compared to healthy donor T cells, whereas BCL2 and MCL1 were not significantly upregulated." (PMID 36045346, 2022). "Expression of the several STAT3-controlled mediators of lymphoma cell proliferation and survival, including Bcl2l1, Bcl6, Casp3, Ccnd3, and Myc, was reduced." (PMID 29433938, 2018). "The CpG-STAT3dODN blocked STAT3 DNA binding and activity, thus reducing expression of downstream target genes, such as MYC and BCL2L1, in human and mouse lymphoma cells." (PMID 29433938, 2018). "The pro-survival BCL-2 proteins: B-cell leukemia/lymphoma-2 (BCL-2/BCL2), myeloid cell leukemia-1 (MCL-1/MCL1) and B-cell lymphoma-extra large (BCL-XL/BCL2L1) are frequently (over)expressed in B-NHL, which plays a crucial role in lymphoma pathogenesis, disease progression, and drug resistance." (PMID 32290241, 2020). "However, BCL6 inhibition also activates BCL6 target genes such as BCL2 and BCL2L1 (BCL-XL), and secondary MCL1, which can sustain lymphoma survival by suppressing the activity of pro-apoptotic BH3 proteins." (PMID 26657288, 2016). "Although BCL6 is known to repress tumor checkpoint genes to support lymphoma cell growth, it could also directly repress BCL2 and BCL2L1 (BCL-XL)." (PMID 26657288, 2016). "Similarly, in lymphoma, let-7a alongside with other miRNAs are upregulated by Romidepsin, decreasing anti-apoptotic proteins such as BCL-2 (B-cell CLL/lymphoma 2) and BCL-XL (BCL2-like 1)." (PMID 31658720, 2019).
myeloma (75 papers, 2005 to 2026). "On the other hand, a reduced expression of STAT3 caused a decreased BCL2L1 expression and induced apoptosis, while a functional STAT3 was necessary for BCL2L1 reporter gene activity in myeloma cells, suggesting that STAT3 activity underlies the high expression of Bcl-xL detected in these tumors." (PMID 33803452, 2021). "Importantly, among the upregulated genes, there were several genes encoding established pro-survival and anti-apoptotic factors in myeloma, including MYC, IRF4, NFKB1/2, BCL2, and BCL2L1." (PMID 38911853, 2024).
gastric cancer (65 papers, 2009 to 2025). A primary or metastatic malignant neoplasm involving the stomach. "In addition, our previous study also demonstrated a strong cytotoxic effect of andrographolide in gastric cancer cell lines by inducing cell death via apoptosis through the induction of proapoptotic proteins, including BCL2L1, EDOG, HRK, and PUMA." (PMID 37958849, 2023).
osteosarcoma (51 papers, 2010 to 2025). A usually aggressive malignant bone-forming mesenchymal neoplasm, predominantly affecting adolescents and young adults. "A study has shown that the cuproptosis-related genes LIAS, PDK1 and BCL2L1 were strongly related to immune cells infiltrating in osteosarcoma, serving as the reliable targets for predicting the patients’ immune response." (PMID 37380924, 2023). "Our results are consistent with experiments in osteosarcoma cell lines that have shown that drug treatment induces growth arrest and increases levels of CDKN1A, MDM2, and BCL2L1." (PMID 24835790, 2014).
acute myeloid leukemia (47 papers, 2010 to 2026). Acute myeloid leukemia (AML) is a group of neoplasms arising from precursor cells committed to the myeloid cell-line differentiation. "In addition, we also evaluated the protein levels of BCLxL (encoded by BCL2L1) and MCL1 in 12 acute myeloid leukemia lines that express both proteins." (PMID 30635584, 2019). "Moreover, SDF1-mediated CXCR4 activation induces resistance to chemotherapy drug Cytarabine, by downregulating microRNA let-7a and promoting transcriptional activation of Myc and BCL2-like 1 isoform 1 (BCL-xL) in acute myeloid leukemia (AML) cells." (PMID 27270649, 2016).
cervical carcinoma (42 papers, 2005 to 2025). A carcinoma arising from either the exocervical squamous epithelium or the endocervical glandular epithelium. "Our study identified colorectal and cervical cancers as having the most frequent BCL2L1 amplification." (PMID 26134786, 2015). "Cervical cancer also has a high percentage of BCL2L1 gains/amplifications although the sample numbers are limited." (PMID 26134786, 2015). "Moreover, LINC00634 exerts oncogenic effects in esophageal squamous cell carcinoma via the miR-342-3p/Bcl2L1 axis, while LINC01535 promotes cervical cancer by targeting the miR-214–EZH2 feedback loop." (PMID 38586313, 2024).
chronic lymphocytic leukemia (41 papers, 2012 to 2026). "The main regulators of apoptosis include both the pro-survival and pro-apoptotic proteins of the Bcl-2 (B-cell CLL/lymphoma 2) family such as Bcl-2 (B-cell lymphoma 2), Bcl-x (BCL2 like 1) with Bcl-xL (B-cell lymphoma extra-large) and Bax (Bcl-2-associated X protein) as well as the caspases." (PMID 35409218, 2022).
non-small cell lung carcinoma (39 papers, 2006 to 2025). A group of at least three distinct histological types of lung cancer, including non-small cell squamous cell carcinoma, adenocarcinoma, and large cell carcinoma. "Previous studies have shown that benzimidazole anthelmintics potentiate the cytotoxicity of BH3 mimetic ABT-263 (a BCL2/BCL2L1 inhibitor) on non-small cell lung cancer." (PMID 32486166, 2020). "Silencing MCL1 (but not BCL2L1 (bcl-xL)) induced cell death in a subset of triple negative breast cancer (TNBC) and non-small cell lung cancer (NSCLC) cell lines and was correlated with the expression of the various BCL2 family members." (PMID 32645016, 2020). "Nuclear BCL2L1 expression correlated among all histologic types with TNM stage IV and the high expression of cytoplasmic BCL2L1 (81.9%) in resected non-small cell lung cancers without any apparent influence on clinical outcome." (PMID 21776270, 2011).
multiple myeloma (38 papers, 2010 to 2025). "The expression of miR‐9‐5p, miR‐181a‐5p, BCL2, MCL1, and BCL2L1 in AL amyloidosis and MM patients was analyzed by t(11:14) status (which was determined by fluorescence in situ hybridization [FISH])." (PMID 36694297, 2023). "By contrast, BCL2L1 expression was lower in AL amyloidosis and MM patients harboring t(11:14) compared with patients without this translocation." (PMID 36694297, 2023). "These miRNAs were downregulated, and BCL2, BCL2L1, and MCL1 genes were upregulated in samples from AL amyloidosis patients compared with MM and HC samples." (PMID 36694297, 2023). "Specifically, BCL2L1, MCL1, and BCL2 were upregulated in AL‐amyloidosis compared with MM and controls." (PMID 36694297, 2023). "Since miRNAs regulate gene expression we used the bioinformatics tools IPA, miRTarBase, and TargetsScan, to explore a connection between the downregulated miRNAs in AL amyloidosis and the BCL2, BCL2L1, and MCL1 genes." (PMID 36694297, 2023).
neuroblastoma (38 papers, 2008 to 2025). Neuroblastoma (NB) is the most common solid, extracranial childhood tumor. "As shown for neuroblastomas, we validated BCL2L1 mRNA as a direct target of miR-342-5p." (PMID 35337159, 2022). "In human neuroblastoma cell lines STAT3 mediates the inhibition of apoptosis by IL-6 and the up-regulation of BIRC5 and BCL2L1 by IL-6 two actions probably involved in the drug resistance of some human neuroblastomas." (PMID 28467792, 2017). "RNAseq analysis revealed high expression of BCL2L1 in MBG3 and BCL2 in neuroblastomas." (PMID 38942989, 2024).
liver cancer (35 papers, 2006 to 2025). An epithelial or non-epithelial malignant neoplasm that arises from the liver. "For example, overexpression of let-7c leads to BCL2L1 repression and induces apoptosis in liver cancer cells, and repression of BCL-XL by let-7c promotes ox-LDL induced endothelial apoptosis." (PMID 31508368, 2019). "BCL2L1 promotes invasion and inhibits apoptosis of liver cancer cells." (PMID 38157373, 2023). "Furthermore, HIGD2A knock-down inhibited the activation of the MAPK/ERK pathway and the expression of BCL2L1, which could promote liver cancer cell apoptosis and suppress cell proliferation." (PMID 37041638, 2023).
bladder cancer (31 papers, 2010 to 2025). "Following the studies in hematologic malignancies, many studies have found amplifications of Bcl-2 family genes, such as MCL1 and BCL2L1 (responsible for encoding Bcl-xL) in solid tumors, such as lung, breast, uterine and bladder cancer, which was confirmed by The Cancer Genome Atlas data." (PMID 37720343, 2023).
small cell lung carcinoma (30 papers, 2011 to 2025). Small cell lung cancer (SCLC) is a highly aggressive malignant neoplasm, accounting for 10-15% of lung cancer cases, characterized byrapid growth, and early metastasis. "In consistence with our study, Loriot and colleagues developed a novel BCL-2 and BCL2L1 inhibitor S44563 and found that it showed radiosensitization in small-cell lung cancer." (PMID 38316463, 2024). "In the Small Cell Lung Cancer Signaling pathway, the molecules BIRC2, BCL2L1, and TRAF, which were commonly upregulated at 6, 12, and 24 h, were associated with the inhibition of apoptosis." (PMID 33520738, 2020).
acute lymphoblastic leukemia (27 papers, 2010 to 2025). Leukemia with an acute onset, characterized by the presence of lymphoblasts in the bone marrow and the peripheral blood. "Ikaros, a transcription factor, represses expression of the BCL2L1 gene, which encodes the anti-apoptotic protein Bcl-XL, in B-cell acute lymphoblastic leukemia (B-ALL)." (PMID 34944749, 2021).
B-cell lymphoma (27 papers, 2006 to 2025). "Conditions linked to BCL2L1 encompass absolute glaucoma and B-cell lymphoma." (PMID 40867920, 2025).
breast tumor (27 papers, 2003 to 2024). "Previous studies have suggested that miR-203b-3p suppresses Bcl-xL protein expression via direct binding to the gene’s mRNA 3’UTR and correlates negatively with BCL2L1 mRNA expression in breast tumors." (PMID 38891019, 2024). "Querying the TCGA database for BCL2L1 amplification in primary breast tumors revealed that 430/1105 (39%) samples harbor BCL2L1 copy number gain and 23/1105 (2%) harbor a high-level focal amplification as determined by GISTIC." (PMID 27153554, 2016). "Furthermore, it was also shown that MCPIP1 functions as a potent tumor suppressor and induces apoptosis of breast tumor cells by selectively enhancing mRNA decay of antiapoptotic gene transcripts, including Bcl2L1, Bcl2A1, RelB, Birc3, and Bcl3." (PMID 28197812, 2017). "In breast tumor, MYC expression correlates positively with miR-203b-3p and miR-203a-3p but negatively with BCL2L1 expression, resulting in formation of a TF-FFL." (PMID 32102656, 2020).
viral infection (27 papers, 2011 to 2025). "In this study, we demonstrated that miR-1276 was able to directly target the sequences in the 3′UTR of BCL2L1 mRNA, which acted as a regulator of cytokines during virus infection." (PMID 27918431, 2016).
lung adenocarcinoma (24 papers, 2005 to 2026). A carcinoma that arises from the lung and is characterized by the presence of malignant glandular epithelial cells. "As previously observed in lung adenocarcinoma cells, the dual inhibition (sequential or simultaneous) of KIF11 and BCL2L1 caused significant levels of apoptosis in SCLC-A or SCLC-N cells, resulting in markedly reduced viability." (PMID 39000337, 2024). "Earlier studies revealed that β-catenin expression is required to maintain a higher level of BCL2L1 in mature T-cells and cisplatin-resistant lung adenocarcinoma cells." (PMID 36733702, 2023). "In patients with lung adenocarcinoma, simultaneous downregulation of exosomal let-7a-5p and elevated expression of BCL2L1 are useful as predictive biomarkers for poor survival." (PMID 30497474, 2018).